PANDAR (promoter of CDKN1A antisense DNA damage activated RNA)
Synonyms: PANDA
Gene: Long non-coding RNA gene on chromosome 6 (36,673,621 to 36,675,126, reverse strand). Ensembl gene ENSG00000281450.
Diseases named in the same sentence as PANDAR in open-access papers:
PANDAR is named in the same sentence as 39 diseases in open-access papers, as found by Europe PMC text mining. Sharing a sentence is not in itself a finding about the gene and the disease. The quoted sentences say what the papers report.
breast carcinoma (19 papers, 2012 to 2025). "Given that silencing PANDAR suppressed the cell growth of breast cancer cells, we sought to determine its underlying mechanisms." (PMID 26927017, 2016). "Recently it was indicated that upregulation of lncRNA PANDAR, leading to the conduction of G1/S transition and promoting cell proliferation in breast cancer cells." (PMID 39971705, 2025). "For instance, lncRNA PANDAR is a novel biomarker of breast cancer, which upregulates proliferation of breast cancer cells." (PMID 33745450, 2021). "This significant increase in MCF-7 cell proliferation suggests that PANDAR is an oncogene regulating breast cancer proliferation." (PMID 37551364, 2021). "PANDAR is an oncogene in breast cancer, potentially facilitating the EMT process and promoting cell proliferation." (PMID 37551364, 2021). "The lncRNA PANDAR regulates the inhibition of the promoter activity of the E-cad gene and promotes breast cancer cell proliferation." (PMID 37551364, 2021). "Although further functional experiments are necessary, the current findings provide new insights into the molecular mechanisms underpinning PANDAR's effect on the EMT process in breast cancer." (PMID 37551364, 2021). "PANDAR, is upregulation in breast cancer, and its silencing in vitro suppresses the transition of breast cancer cells from G1 to the S phase, resulting in a decrease in tumor cell proliferation." (PMID 33291485, 2020). "In our results, the silencing of PANDAR did not affect the apoptosis of breast cancer cells, suggesting that appropriate gene stress is required for PANDAR silencing-mediated apoptosis of breast cancer cells." (PMID 26927017, 2016). "Several controversially discussed studies have demonstrated that PANDAR is upregulated in hepatocellular carcinoma, gastric cancer, and breast cancer, indicating its potentially complex role in cancer." (PMID 27608009, 2016). "In our study, we found that lncRNA PANDAR was significantly up-regulated in breast cancer tissues as well as breast cancer cells." (PMID 26927017, 2016). "Altogether, these results indicate that the down-regulation of PANDAR represses the G1/S transition of breast cancer cells." (PMID 26927017, 2016). "In this study, we investigated the role of lncRNA PANDAR in the progression of breast cancer and found that PANDAR was up-regulated in breast cancer tissues and cell lines." (PMID 26927017, 2016). "As mentioned, PANDAR is upregulated in breast cancer tissues, as well as in breast cancer cell lines and functions as a tumor-promoting lncRNA by regulating G1/S transition." (PMID 27608009, 2016). "The silencing of PANDAR suppresses the G1/S transition of breast cancer cells, leading to decreased cell growth." (PMID 26927017, 2016). "Consistent with the observation in tissues, PANDAR level was up-regulated in breast cancer cells compared with immortalized breast cells." (PMID 26927017, 2016). "We found that PANDAR was up-regulated in breast cancer cells compared to normal breast epithelial cells, agreeing with our findings in breast cancer tissues." (PMID 26927017, 2016). "PANDAR expression level increased from G1 to S phase and remained steady or changed slightly during G2, M, and G1 phases, implying that PANDAR plays an important role in the G1/S transition of breast cancer cells." (PMID 26927017, 2016). "Besides, in 2022, a study analyzed the expression levels of lncRNAs in the plasma of 51 breast cancer patients, the findings revealed a significant correlation between plasma PANDAR expression and family history in patients with metastatic breast cancer." (PMID 40713854, 2025). "By inhibiting p16INK4A expression, PANDAR modulates G1/S arrest in breast cancer cells." (PMID 37551364, 2021). "PANDAR was overexpressed in Michigan cancer foundation 7 (MCF-7) breast cancer cells." (PMID 37551364, 2021). "PANDAR was demonstrated to modulate G1/S arrest in breast cancer cells via p16INK4A downregulation." (PMID 37551364, 2021).
breast carcinoma (continued). "SPRY4-IT1, GAS5, PANDAR and H19 are lncRNAs dysregulated in breast cancer." (PMID 33291485, 2020). "PANDAR was significantly up-regulated in breast cancer compared to breast cysts tissues." (PMID 26927017, 2016). "The knockdown of PANDAR reduced cell growth and colony formation of breast cancer cells." (PMID 26927017, 2016). "Altogether, these results indicate that PANDAR modulates the proliferation of breast cancer cells." (PMID 26927017, 2016). "The contradictory functions of PANDAR in cancers as observed in our results and Han’s report might be due to the differences between the properties of breast cancer and NSCLC." (PMID 26927017, 2016). "Our findings suggest that PANDAR could function as a tumor-promoting gene and regulate the cell cycle of breast cancer cells." (PMID 26927017, 2016). "In this study, we found that PANDAR was up-regulated in breast cancer tissues and cell lines." (PMID 26927017, 2016). "The knockdown of PANDAR suppresses G1/S transition of breast cancer cells." (PMID 26927017, 2016). "Our study suggests that PANDAR could function as a tumor-promoting gene in breast cancer by regulating G1/S transition." (PMID 26927017, 2016). "We demonstrated mechanistically that PANDAR regulates the G1/S transition of breast cancer cells." (PMID 26927017, 2016). "Our findings may supply a strategy for targeting the PANDAR/Bmi1/p16INK4A axis as a novel therapeutic application for breast cancer patients." (PMID 26927017, 2016). "Our findings indicate that PANDAR may function as a cell cycle regulator of breast cancer cells." (PMID 26927017, 2016). "The PANDAR/Bmi1/p16INK4A axis could serve as novel targets for breast cancer therapy." (PMID 26927017, 2016). "First, we established whether the silencing PANDAR affected the cell cycle of breast cancer cells." (PMID 26927017, 2016). "Next, we examined whether PANDAR regulated the apoptosis of breast cancer cells." (PMID 26927017, 2016). "In breast cancer, inhibition of lncRNA PANDAR reduces cancer cell proliferation and invasion, while lncRNA SPRY4-IT1 promotes breast cancer cell proliferation and stemness by targeting miR-6882-3p." (PMID 41230330, 2025). "As indicated in the extant literature, miR-20a-5p has been reported to contribute to the development of breast cancer by affecting the regulation of SPRy4-IT1, SRCIN1, and PANDAR gene expression." (PMID 40686703, 2025). "Numerous researches have revealed that miR-20a-5p is vital for the development and prognosis of breast cancer through the targeted regulation of genes such as SPRy4-IT1, SRCIN1 and PANDAR, and have also provided a breakthrough for drug design and synthesis of breast cancer." (PMID 35577802, 2022). "Mechanistically, the silence of PANDAR led to the G1/S arrest but did not affect the apoptosis of breast cancer cells." (PMID 26927017, 2016). "Taken together, these results indicate that PANDAR regulates the cell cycle progression but not the apoptosis of breast cancer cells." (PMID 26927017, 2016). "First, we investigated the expression of PANDAR in a panel of breast cancer cell lines and immortalized normal breast epithelial cells." (PMID 26927017, 2016). "Because PANDAR level was notably elevated in breast cancer tissues compared to non-cancerous tissues, we inferred that PANDAR might play important roles in tumor biology." (PMID 26927017, 2016).
gastric cancer (8 papers, 2017 to 2025). A primary or metastatic malignant neoplasm involving the stomach. "This study demonstrated that miR-637 reverses the inhibitory effects of PANDAR silencing on gastric cancer cell proliferation and metastasis, indicated that miR-637 is involved in regulating PANDAR-mediated processes in GC cells." (PMID 40713854, 2025). "It was found in previous studies that PANDAR was upregulated in various cancers, including gastric cancer, cholangiocarcinoma, hepatocellular carcinoma, and clear cell renal cell carcinoma." (PMID 31850222, 2019). "Gastric cancer patients with a high expression of PANDAR showed significantly shorter 5-year overall survival rates than those with low expression of PANDAR." (PMID 29416011, 2018). "Whether this mechanism also exists in GC and how PANDAR/miR-637 axis affects the biological behavior of gastric cancer are still unclear." (PMID 40713854, 2025). "PANDAR is a promoter of CDKN1A antisense DNA damage activated RNA and increased expression of PANDAR has been indicated to predict poor prognosis in cervical and gastric cancer." (PMID 33926464, 2021).
non-small cell lung carcinoma (8 papers, 2015 to 2020). A group of at least three distinct histological types of lung cancer, including non-small cell squamous cell carcinoma, adenocarcinoma, and large cell carcinoma. "The results indicated that increased PANDAR expression was closely related to reduced OS in colorectal cancer, whereas reduced PANDAR expression was associated with decreased OS of non-small cell lung cancer." (PMID 31850222, 2019). "In addition, our review revealed that elevated expression level of PANDAR was associated with decreased OS in colorectal cancer, whereas the reduced PANDAR expression level was significantly related to poor OS in non-small cell lung cancer." (PMID 31850222, 2019). "Recently, it has been reported that the expression of PANDAR was downregulated in non-small cell lung cancer (NSCLC) and a low level of PANDAR was associated with a poor prognosis." (PMID 28545465, 2017). "Here, we investigated the the role of lncRNA PANDAR in the progression of non-small cell lung carcinoma (NSCLC)." (PMID 25719249, 2015). "Secondly, PANDAR has been shown to promote cell survival in non-small cell lung carcinoma (NSCLC) in which low expression level of PANDAR permits NF-YA to up-regulate Bcl2 expression, an anti-apoptotic gene." (PMID 32106407, 2020). "Moreover, we discovered that high PANDAR expression was closely related to decreased OS in colorectal cancer (pooled HR 3.43, 95%CI 2.06–5.72) and reduced expression level of PANDAR was markedly related to poor OS (pooled HR 0.65, 95%CI 0.45–0.88) in non-small cell lung cancer." (PMID 31850222, 2019). "For instance, PANDAR was downregulated in non-small cell lung cancer (NSCLC), and the low level of PANDAR indicated a poor prognosis." (PMID 28545465, 2017).
bladder cancer (7 papers, 2016 to 2021). "In contrast, PANDAR was found to be upregulated in hepatocellular and in bladder carcinoma, and a high level of PANDAR was associated with a poor prognosis." (PMID 28545465, 2017). "Increased PANDAR expression has been associated with poor prognosis, likely due to the ability of PANDAR to promote cell growth and metastasis in bladder cancer cells." (PMID 27206339, 2016). "In contrast to this, several cancer types like gastric cancer, hepatocellular carcinoma and bladder cancer revealed increased PANDAR levels that correlated with a higher TNM stage and poor prognosis." (PMID 29434205, 2018). "Further in vitro analysis of bladder cancer revealed that PANDAR upregulation leads to proliferation, while PANDAR knockdown results in apoptosis." (PMID 29434205, 2018). "Inhibited cell proliferation/migration and induced cell apoptosis by silencing PANDAR were observed in bladder cancer cells." (PMID 27206339, 2016). "PANDAR was up-regulated in bladder cancer cell lines compared to normal urothelial cell line SV-HUC-1." (PMID 27206339, 2016). "We demonstrated that silencing PANDAR significantly inhibited proliferation/migration and induced apoptosis of the bladder cancer cells." (PMID 27206339, 2016). "In order to understand the biological functions of lncRNA PANDAR, we detected the cell proliferation, apoptosis and migration by silencing and overexpressing lncRNA PANDAR in the related bladder cancer cell lines." (PMID 27206339, 2016). "LncRNA PANDAR was up-regulated in bladder cancer tissues compared to pair-matched adjacent normal tissues." (PMID 27206339, 2016). "Further experiments demonstrated that inhibited cell proliferation/migration and induced apoptosis by silencing PANDAR were also observed in bladder cancer cells." (PMID 27206339, 2016). "Additionally, PANDAR plays an oncogenic role in bladder cancer by inducing cell proliferation and suppressing proapoptotic pathways." (PMID 37551364, 2021). "In contrast, PANDAR was significantly upregulated in bladder cancer." (PMID 28545465, 2017). "In this study, we aimed to figure out the role of PANDAR in bladder cancer." (PMID 27206339, 2016). "Furthermore, over expression of PANDAR in bladder cancer cells promoted the proliferation/migration and suppressed apoptosis." (PMID 27206339, 2016). "Moreover, over expression of PANDAR in bladder cancer cells promoted the proliferation/migration and suppressed apoptosis." (PMID 27206339, 2016). "Cumulatively, these findings demonstrate that PANDAR plays oncogenic roles in bladder cancer and PANDAR may serve as a potential prognostic biomarker and therapeutic target of bladder cancer." (PMID 27206339, 2016). "At 48 h after transfection, the related expression level of PANDAR was determined by qRT-PCR and the results showed that the relative level of PANDAR in bladder cancer cells was significantly down-regulated by the PANDAR siRNA and up-regulated by the pcDNA3.1-PANDAR." (PMID 27206339, 2016). "Bladder cancer cells were cultured and then we inhibited PANDAR expression by transfecting PANDAR specific siRNA and enhanced PANDAR expression by transfecting a PANDAR expression vector (pcDNA3.1-PANDAR)." (PMID 27206339, 2016). "We further determined whether PANDAR promotes cell proliferation in bladder cancer." (PMID 27206339, 2016). "However, the clinical significance and molecular mechanism of PANDAR in bladder cancer is still unknown." (PMID 27206339, 2016). "We further determined whether PANDAR promotes cell migration in bladder cancer." (PMID 27206339, 2016). "We further determined whether PANDAR suppresses cell apoptosis in bladder cancer." (PMID 27206339, 2016). "In this study, we found that lncRNA PANDAR was significantly up-regulated in bladder cancer tissue compared with paired-adjacent nontumorous tissues in a cohort of 55 bladder cancer patients." (PMID 27206339, 2016).
bladder cancer (continued). "In the present study, we found that lncRNA PANDAR was significantly up-regulated in bladder cancer tissues than that in corresponding non-tumor bladder tissues." (PMID 27206339, 2016). "We found that PANDAR was significantly up-regulated in bladder cancer tissues compared with paired-adjacent nontumorous tissues in a cohort of 55 bladder cancer patients." (PMID 27206339, 2016).
clear cell renal cell carcinoma (6 papers, 2017 to 2021). "A lncRNA panel including lncRNA-LET, PVT1, PANDAR, PTENP1, and linc00963, were identified to distinguish clear cell renal cell carcinoma from healthy controls." (PMID 29029437, 2017).
colorectal cancer (5 papers, 2016 to 2022). A primary or metastatic malignant neoplasm that affects the colon or rectum. "Treated by curcumin, Lnc NBR2, Lnc KCNQ1OT1, Lnc PANDAR, and Lnc CCAT1 could prove to be potentially effective target molecules in the treatment progress of colorectal cancer." (PMID 36291546, 2022).
ovarian carcinoma (5 papers, 2018 to 2024). A malignant neoplasm originating from the surface ovarian epithelium. "To investigate whether lncRNA PANDAR was associated with ovarian cancer chemosensitivity, we examined PANDAR expression profile in cisplatin-sensitive and cisplatin-resistant cells of OC." (PMID 30375398, 2018). "To further investigate the biological functions of PANDAR in ovarian cancer, we created isogenic PANDAR Venus knock-in HO-8910PM cell line and PANDAR Venus knockdown (shPANDAR) A2780 cell line." (PMID 30375398, 2018). "However, in the DNA damage response to cisplatin, SFRS2 was identified as an oncogene interacting with lncRNA PANDAR to promote cisplatin resistance in ovarian cancer cells." (PMID 30375398, 2018). "Besides, PANDAR location in ovarian cancer cell also varies with the extended response time during cisplatin treatment, further investigation might focus on how this dynamic cellular location move forward." (PMID 30375398, 2018). "To confirm this, we measured PANDAR levels in A2780 and HO-8910 cells following treatments by chemo-drugs doxorubicin (Dox), paclitaxel (PTX), and cisplatin (CDDP), as they were commonly used in clinical ovarian cancer chemotherapeutics." (PMID 30375398, 2018). "Last but not least, the role of PANDAR in chemoresistance was confirmed in patients with ovarian cancer." (PMID 30375398, 2018).